MTHFD2 (methylenetetrahydrofolate dehydrogenase (NADP+ dependent) 2, methenyltetrahydrofolate cyclohydrolase)
Diseases named in the same sentence as MTHFD2 in open-access papers (continued):
Sharing a sentence is not in itself a finding about the gene and the disease.
tumor (continued). "The fact that these five genes (MTHFD2, EIF4E, RMI1, CAV1 and HIF1A) are all very relevant in tumor biology further emphasizes a role of Wig-1 in the regulation of cell cycle and cell proliferation, as well as tumor onset, progression and metastasis." (PMID 26672765, 2016). "The aim of the present study was to assess the association between primary tumor expression of six selected folate pathway genes, ABCC3, RFC‐1, PCFT, MFT, MTHFD2, and TYMS, and tumor response as well as 3‐year progression‐free survival (PFS) of patients with mCRC." (PMID 40357991, 2025). "For instance, we did not explore how downregulation of MTHFD2 promotes cellular senescence and its impact on tumor immunity during this process." (PMID 39668825, 2024). "Specifically, MTHFD2 expression was significantly increased in ESCA samples, indicating its upregulation in the disease context, suggesting its potential involvement in promoting tumor growth and progression." (PMID 38373930, 2024). "In both the unpaired samples, containing 35 adjacent normal tissues and 552 tumor tissues, and 23 paired samples, the MTHFD2 mRNA level in tumor samples is significantly increased than that in adjacent normal samples." (PMID 37484807, 2023). "MTHFD2 is overexpressed in a variety of tumours but exhibits low or no expression in most differentiated adult tissues." (PMID 37480214, 2023). "Consistently, the infiltration of several typical anti-tumor TIICs, including CD8+ T cell, NK cell, type 1 T helper cell, dendritic cell, and macrophage, was significantly higher in patients with high MTHFD2 expression." (PMID 38130721, 2023). "Importantly, an MTHFD2 inhibitor, DS18561882, combined with enzalutamide can significantly inhibit CRPC cell proliferation in vitro and tumor growth in vivo." (PMID 35382861, 2022). "This suggests that tumor basal MTHFD2 but not IFN-γ-elevated MTHFD2 is involved in the initial process of IFN-γ-induced PD-L1 expression." (PMID 33782411, 2021). "Elevated MTHFD2 expression was found in CRC, related to tumor cell invasiveness." (PMID 34200820, 2021). "Considering the potential tumor promoting role of MTHFD2 in HNSCC, activation of mast cells might suppress anti-tumor immunity in HNSCC." (PMID 32933024, 2020). "The expression level of MTHFD2 was elevated in HNSCC, and upregulation of MTHFD2 was closely correlated with poor prognosis of HNSCC, indicating that MTHFD2 might play a tumor promoting role in the progression of HNSCC." (PMID 32933024, 2020). "In conclusion, MTHFD2 overexpression is closely correlated with unfavorable prognosis of HNSCC, and it might play an important role in modulating the tumor immune microenvironment." (PMID 32933024, 2020). "MTHFD2 is highly expressed in the mitochondria and nucleus of multiple types of tumor cells, but not in non-transformed cells." (PMID 32111066, 2020). "These morphological changes, together with the correlation of MTHFD2 or PAICS expression to INSS, led us to probe whether MTHFD2 and PAICS play roles in malignant transformation and tumor aggressiveness." (PMID 31624245, 2019). "The MTHFD2 protein is specifically expressed in transformed cells, but not the stroma surrounding the tumor tissues." (PMID 28210221, 2017). "A multivariate analysis of MTHFD2 expression in the same dataset showed that tumor grade was an independent predictor of survival (data not shown), whereas MTHFD2 expression alone was not sufficient to predict prognosis." (PMID 23295955, 2013). "In agreement with our preliminary results from human tissues, MTHFD2 is known to be expressed in tumor cells, but not in normal cells in adult mice." (PMID 23295955, 2013). "In parallel, upon RUNX2 knockdown, we have observed a predominant and strong downregulation of gene nodes known to be implicated in EOC tumorigenesis (PTGS1/COX1, FGF2, IL1A, Sapk, C/ebp, SELE, UBQLN1, PSAT1, ALDH1A1, GDF15, MTHFD2), including EOC tumor invasion/metastasis (MMP1, MMP13, Creb);." (PMID 24124450, 2013).
tumor (continued). "Clearly, the situation may turn out to be different in rapidly dividing tumor cells with their elevated demand of nucleotides, which also frequently induce serinogenesis and the mitochondrial folate-metabolizing enzymes SHMT2 and MTHFD2." (PMID 41373508, 2025). "The long journey to the isolation and characterization of MTHFD2 began with the identification by Scrimgeour and Huennekens in 1960 of a distinctive enzymatic activity (NAD+-dependent methylenetetrahydrofolate dehydrogenase activity) in Ehrlich ascite tumour cells." (PMID 41303507, 2025). "This analysis confirmed the association of TYMS, TK1, SHMT2, MTHFD2, and DHFR expressions with the main prognosis markers (hypermutation, MSI, iCluster, expression subtype, and tumour stage) while MTHFD1, and not MTHFD2, was more strongly associated with methylation status." (PMID 38540202, 2024). "However, there was no statistical significance between MTHFD1, MTHFD1L, or MTHFD2 and the tumor microenvironment in OSCC." (PMID 35693982, 2022). "Strikingly, MTHFD2 raises the basal and IFN-γ-stimulated PD-L1 expression in both basal and IFN-γ-stimulating conditions, which could be the epitome of the linking of onco-metabolic genes and tumor immunoresistance." (PMID 36138435, 2022). "Similarly, it was reported that miR-940 could reversely regulate CKS1, MACC1, MTHFD2 and SPOCK1 in tumors, indicating its significant function in tumor occurrence and development." (PMID 35297315, 2022). "MTHFD2 is a NAD+-dependent enzyme with methylenetetrahydrofolate dehydrogenase and cyclohydrolase activity, which has been suggested to be a key participant in the metabolic reprogramming and tumor cell-sustaining proliferative capacity independently of dehydrogenase activity." (PMID 35135596, 2022). "As a result of tumor immunity analysis, MTHFD2L expression was found to be negatively related to the Estimate-Stromal-Immune score in OSCC; however, there was no statistical significance between the Estimate-Stromal-Immune score and MTHFD1, MTHFD1L, or MTHFD2 in OSCC." (PMID 35693982, 2022). "It was reported that MTHFD2 is expressed in the developing embryo, but is absent in most healthy adult tissues, and overexpression of MTHFD2 alone was sufficient to promote tumor cell proliferation." (PMID 34604366, 2021). "The tumor-selective cytotoxic mechanism of β-lap was further confirmed in vivo using xenograft animal models of radiation resistant HNSCC, which revealed cooperative mechanisms of tumor suppression and extensive necrosis in MTHFD2 knockdown tumors treated with combined β-lap and ionizing radiation." (PMID 33262939, 2020). "Finally, the exact effect of MTHFD2 downregulation on the tumor microenvironment remains unclear due to the lack of single-cell sequencing or multi-parameter flow cytometry analyses." (PMID 39668825, 2024). "Moreover, recent findings have uncovered a nonmetabolic role of MTHFD2 in tumour immune evasion." (PMID 37480214, 2023). "Furthermore, we observed MTHFD2 target engagement with TH9619 in vivo by performing CETSA on tumor samples, whereas no stabilization could be observed in the vehicle-treated animals, or those on TYMS with TH9619." (PMID 35228749, 2022). "The results revealed that MTHFD2, but not MTHFD1, was overexpressed in tumor tissues vs. matched paracancerous tissues." (PMID 38723197, 2024).
infection (5 papers, 2020 to 2025). The state of being infected such as from the introduction of a foreign agent such as serum, vaccine, antigenic substance or organism. "To test the importance of mitochondrial 1C (mito-1C) metabolism in the changes in mtDNA during infection, we generated cells deficient for MTHFD2." (PMID 40811546, 2025). "As expected, infection induced MTHFD2 and SHMT2 in an ATF4-dependent manner." (PMID 40811546, 2025). "Infection drove increases in the levels of ATF4 targets Atf3, Shmt2, and Mthfd2, similar to our results in cultured cells." (PMID 40811546, 2025). "Cells were transfected with multiplicity of infection (MOI) (shMTHFD2‐L) and high MOI (shMTHFD2‐H), and shMTHFD2‐H significantly suppressed the protein expression of MTHFD2 when compared with shMTHFD2‐L in both A549 and H1299." (PMID 31778025, 2020). "Infection did not increase mtDNA levels in MTHFD2 KO cells, unlike in WT cells." (PMID 40811546, 2025).
adenocarcinoma (3 papers, 2020 to 2024). A common cancer characterized by the presence of malignant glandular cells. "Conversely, one sample with adenocarcinoma features showed less CPT1A associated with less SHMT2, MTHFD2, and PSAT1 expression." (PMID 33218188, 2020).
cardiovascular diseases (3 papers, 2018 to 2023). "Most of the current studies on MTHFD2 are related to tumors and cardiovascular diseases, and there are no reports related to KOA." (PMID 35785145, 2022).
hematologic malignancies (1 paper, 2020). "The only non-transformed cell induction of MTHFD2 was observed in lymphocyte activation, indicating the role of MTHFD2 in normal hematopoietic cells as well as in the tumorigenesis process of hematologic malignancies." (PMID 32111066, 2020).
mitochondrial disease (1 paper, 2021). "Methylenetetrahydrofolate dehydrogenase 2 (MTHFD2), a metabolic enzyme that facilitates one-carbon metabolism, was found to be upregulated in mitochondrial diseases." (PMID 33920115, 2021).
MTHFD2 also shares sentences with these, for which no sentence is quoted: breast tumor (2 papers); cholangiocarcinoma (2); colon adenocarcinoma (2); Ewing sarcoma (2); multiple myeloma (2); acute leukemia (1); acute lymphoblastic leukemia (1); Astrocytoma (1); bacterial infection (1); Burkitt lymphoma (1); cervical cancer (1); cervical squamous cell carcinoma (1); chronic myeloid leukemia (1); Clear Cell Renal Cell Carcinoma (1); colorectal (1); Down syndrome (1); endocervical adenocarcinoma (1); endometriosis (1); esophageal squamous cell carcinoma (1); gynecologic cancer (1); head and neck cancer (1); hyperhomocysteinemia (1); lung squamous cell carcinoma (1); meningioma (1); mesothelioma (1); metabolic disorders (1); myocardial infarction (1); myopathy (1); nasopharyngeal carcinoma (1); nephrotic syndrome (1).
A further 12 diseases each share a sentence with MTHFD2 in 1 paper.